AQP7 (aquaporin 7)
Diseases named in the same sentence as AQP7 in open-access papers (continued):
Sharing a sentence is not in itself a finding about the gene and the disease.
type 2 diabetes (17 papers, 2013 to 2025). "The human Aqp7 gene is present in a chromosomal region that has been associated with type 2 diabetes and metabolic syndrome." (PMID 37681902, 2023). "Other variants of Aqp7 gene were significantly associated with type 2 diabetes or glycated hemoglobin." (PMID 37681902, 2023). "Altogether, data suggest that some genetic variants of Aqp7 gene can be associated with metabolic features playing a role in type 2 diabetes." (PMID 37681902, 2023). "In a cohort of Caucasian subjects, a subject with the G264V mutation in the AQP7 gene presented type 2 diabetes, overweight and extremely low glycerol levels." (PMID 31614661, 2019). "Human studies remain scarce and controversial, with some rare cases of loss-of function mutations of the AQP7 gene being associated with the onset of type 2 diabetes." (PMID 29675407, 2018). "Moreover, a study performed in 977 Caucasian individuals detected a single-nucleotide polymorphism (A593G) in the human AQP7 gene promoter that was related to decreased AQP7 expression in the adipose tissue as well as with type 2 diabetes." (PMID 29675407, 2018). "Metformin, the first-line drug for treating type 2 diabetes, has seen its latest anti-diabetic effects research focused on its positive impact on AQP7 expression in the pancreas." (PMID 39456161, 2024). "Despite the detection of several AQPs in the endocrine pancreas, only AQP7 has been shown to date to participate in insulin secretion, and to undergo deregulation in type 2 diabetes that can be rescued by hypoglycemic drugs." (PMID 37681902, 2023). "In humans, the AQP7 gene is localized to a chromosomal region with reported linkage to type 2 diabetes and metabolic syndrome." (PMID 31614661, 2019). "We aimed to investigate the associations between genetic variants in AQP7 and AQP9 genes and the risk of type 2 diabetes (T2DM) in Chinese population." (PMID 30598999, 2018). "Furthermore, in a model of obese rats with type 2 diabetes, AQP7 mRNA expression in adipose tissue was upregulated, possibly contributing to an augmented glycerol input for hepatic gluconeogenesis and subsequent hyperglycemia." (PMID 35187089, 2022). "In type 2 diabetes, an increased level of AQP7 protein abundance in skeletal muscles can contribute to excess lipid accumulation in skeletal muscles, similar to our results, and the increased expression level of AQP7 gene can contribute to a higher IMF content in the muscles of Wei pigs." (PMID 32138348, 2020). "In addition, the human aqp7 gene is localized in a chromosomal region with reported linkage to the metabolic syndrome and type-2-diabetes (T2D)." (PMID 29300344, 2018). "In this context, the design of novel small-molecule modulators of AQP7 expression/function may have clinical applications in the therapy of type 2 diabetes." (PMID 29675407, 2018). "Interestingly, Metformin, a hypoglycemic drug used to treat diabetic patients, rescued AQP7 expression to induce insulin secretion in the rat in vitro and in vivo models of type 2 diabetes by suppressing the Mitogen-Activated Protein Kinase p38 and c-Jun N-terminal kinase (JNK) pathway." (PMID 37681902, 2023). "Rosiglitazone was also shown to increase AQP7 mRNA levels in the mesenteric fat and induce glycerol kinase mRNA expression in both fat depots on OLETF rats, a type 2 diabetes model." (PMID 35187089, 2022). "The coordinated regulation of glycerol channels in adipose tissue (AQP7) and the liver (AQP9) has been suggested as an important contributor to the pathophysiology of type-2-diabetes mellitus, as it would provide glycerol for hepatic synthesis of glucose and triglycerides." (PMID 33193093, 2020). "Very recent data showed decreased Aqp7 mRNA in islets from type 2 diabetic patients, a negative correlation between Aqp7 mRNA expression in islets and body mass index, a strong association between a genetic variant of the Aqp7 gene and random glucose and fasting glucose adjusted for body mass index." (PMID 37681902, 2023).
type 2 diabetes (continued). "Evidence regarding the relationship between AQP7 expression and type 2 diabetes is still lacking." (PMID 32821266, 2020).
breast carcinoma (13 papers, 2011 to 2026). "Commending this AQP as a cancer-specific therapeutic target, AQP7 was prognostic for overall survival in patients and decreased expression caused a reduction of primary tumors and metastasis in mouse breast cancer models." (PMID 38319972, 2024). "Since diminished expression of AQP7 in a mouse breast cancer model caused reduced primary tumor burden, and cell proliferation in leukemia cells is dependent on intracellular glycerol levels, we investigated the translational properties of Z433927330." (PMID 38319972, 2024). "In mouse breast cancer models, reduced expression of Aqp7 caused reduced primary tumor burden and lung metastasis." (PMID 35847914, 2022). "Of these AQPs, reduced expressions of AQP6 or AQP7 were associated with responders to aromatase inhibitors for Luminal A subtype breast cancer, whereas reduced AQP8 expression was associated with responders to anthracycline treatment for Luminal A subtype breast cancer." (PMID 36212456, 2022). "AQP6 and AQP7 can increase the resistance to oxidative stress in mesothelioma cells and breast cancer cells, respectively, with AQP7 also altering cancer cell metabolism." (PMID 39941100, 2025). "Previously, we discovered that Aquaporin-7 (human AQP7/mouse Aqp7), a water and glycerol channel, is a novel regulator of breast cancer." (PMID 39123442, 2024). "Recently, AQP7 was identified as a novel regulator of breast cancer and reduced expression resulted in decreased primary tumor burden and lung metastasis." (PMID 38319972, 2024). "We previously found that genetic inhibition of Aqp7 reduces primary tumor burden and metastasis in breast cancer." (PMID 39123442, 2024). "Patients with tumors that responded to any endocrine therapy had reduced AQP7 expression for Luminal A subtype breast cancer." (PMID 39123442, 2024). "Given the correlation of AQP7 with breast cancer and its involvement in glycerol transport and lipid homeostasis, we investigated AQP7 as a metabolic target for cancer therapy." (PMID 39123442, 2024). "The human genome encodes four aquaglyceroporins AQP3, AQP7, AQP9, and AQP10 and recently AQP7 was identified as a novel regulator of breast cancer." (PMID 38319972, 2024). "In a mouse model of breast cancer, lower AQP7 expression resulted in a reduction in primary tumor burden and lung metastases, thus suggesting that AQP7 is a prognostic indicator of overall survival in breast cancer patients." (PMID 37091789, 2023). "The mRNA expression levels of AQP8, AQP9, and AQP10 were upregulated, while those of AQP3, AQP4, AQP5, and especially AQP7, were downregulated in breast cancer based on the Oncomine database." (PMID 36212456, 2022). "Our study on the role of AQP7 in breast cancer evaluated AQP7 expression in human and mouse breast cancer and normal tissues." (PMID 36212456, 2022). "In mouse breast cancer models, lipid accumulation in Aqp7 KD tumors was detectable by Oil Red O staining." (PMID 35972604, 2022). "Unexpectedly, the gene hub Aquaporin-7 (Aqp7) was identified as a novel regulator of breast cancer and that AQP7 was prognostic of overall survival in patients with breast cancer." (PMID 35847914, 2022). "CD36 and AQP7, which mediate the transport of fatty acids and water/glycerol, respectively, are expressed in tumors including breast cancer and are involved in cell migration and tumor metastasis." (PMID 33083529, 2020). "In addition, AQP7 knockdown in breast cancer cells resulted in decreased oxidative stress tolerance." (PMID 37681917, 2023). "AQP7 knockdown in breast cancer cells resulted in decreased oxidative stress tolerance." (PMID 37681917, 2023). "Indeed, metabolomics and lipid profiling of breast cancer cells revealed that AQP7 was involved in lipid metabolism, glutathione metabolism, and urea/arginine metabolism." (PMID 37681917, 2023).
breast carcinoma (continued). "In this review, we discuss the roles of AQP1, AQP3, AQP4, AQP5, and AQP7 in breast cancer progression and metastasis, including the role of AQPs in the tumor microenvironment, to highlight potential contributions of stromal-derived to epithelial-derived AQPs to breast cancer." (PMID 36212456, 2022). "In other words, AQP7, as a critical regulator, might eventually lead to the development of more effective therapeutics in breast cancer." (PMID 35972604, 2022). "However, Aqp7 is often clearly localized to the plasma membrane of mammary cancer cells compared to normal mammary tissue across these tumor types." (PMID 36212456, 2022). "Unexpectedly, increased AQP7 and AQP8 levels were associated with better survival times in glioma, ovarian and endometrial cancers, and increased AQP11 with better survival in colorectal and breast cancers." (PMID 32679804, 2020). "Moreover, RT-PCR analysis revealed that AQP3 and AQP7 mRNA expression was also observed in human breast cancer MCF7 cells, in addition to AQP5 expression." (PMID 22145049, 2011). "Therefore, elevated levels of CD36, AQP7, LIPE, and AKR1C1 in mammary epithelial cells may serve as promising indicators for identifying high-risk breast cancer groups." (PMID 40868150, 2025). "Moreover, a study found that breast cancer patients with high AQP7 mRNA expression had reduced overall survival (OS) compared to patients with low AQP7 mRNA expression and high AQP9 mRNA expression was associated with a worse relapse-free survival (RFS) and OS." (PMID 37681917, 2023). "Because of this connection between AQP7 expression and endocrine therapy response, we investigated if AQP inhibition improved the therapeutic efficacy of endocrine therapy in breast cancer in vitro." (PMID 39123442, 2024). "AQP1, AQP3, AQP4, AQP5, AQP7, and AQP9 expression were evaluated because these AQPs are expressed in breast tumors and have begun to be characterized as having roles in breast cancer progression and metastasis." (PMID 39123442, 2024). "Transcriptomic analyses using the Human Protein Atlas database revealed higher mRNA levels of several AQPs in human breast cancer, namely AQP1, AQP3, AQP5, AQP7, AQP9 and AQP11, when compared to overall median AQP expression levels in the biopsies." (PMID 37681917, 2023). "A previous study performing transcriptomic analyses on breast cancer biopsies revealed increased mRNA expression of AQP1, AQP3, AQP5, AQP7, AQP9 and AQP11 when compared to overall median AQP levels in the biopsies." (PMID 37681917, 2023). "Next, we outline the roles in breast cancer of AQP1, AQP3, AQP4, AQP5, and AQP7, which are the only AQPs that have begun to be characterized as having roles in breast cancer progression and as potential prognostic markers." (PMID 36212456, 2022). "Analysis of The Cancer Genome Atlas (TCGA) showed that AKR1C1, AQP7, CD36, and LIPE display low genomic alteration frequency in breast cancer, and only CD36 expression has prognostic value (P = 0.005)." (PMID 33083529, 2020). "Given that numerous studies have shown the role of AQP3 and AQP7 overexpression in promoting breast cancer, the combined inhibition of AQP3 and AQP7 could be a useful strategy in the treatment of breast cancer progression and metastasis." (PMID 39123442, 2024). "We previously identified AQP7 as a negative prognostic marker of overall survival and metastasis in breast cancer patients." (PMID 39123442, 2024). "It is still unknown if AQP7 facilitates increased MMP secretion, and it is unknown how the combinatory effects of the three AQPs affect MMP secretion in breast cancer cells." (PMID 37681917, 2023). "We identified AQP7 as a negative prognostic marker of overall survival and metastasis in breast cancer patients." (PMID 36212456, 2022). "Therefore, AQP7 expression was higher in tumors from breast cancer patients that did not respond to endocrine therapy than it was compared to those tumors that did respond." (PMID 39123442, 2024).
breast carcinoma (continued). "Conversely, increased levels of AQP7 and AQP8 expression correlated with longer survival times, suggesting a possible protective role in cancer that could be analogous to effects of AQPs 4 and 11 in breast cancer." (PMID 32679804, 2020). "Transcriptomic analysis revealed that the three aquaglyceroporins, AQP3, AQP7 and AQP9, but not AQP10, are overexpressed in human breast cancer." (PMID 37681917, 2023). "Systematic analysis of how AQP7 and AQP9 affect the response of breast cancer cells to conventional anticancer therapies is still lacking." (PMID 37681917, 2023).
diabetes (10 papers, 2012 to 2025). "AQP7 is not only upregulated in mice with streptozotocin-induced diabetes mellitus, but also upon 72 h of fasting." (PMID 31027200, 2019). "An increase in the expression of AQP7 mRNA and protein was reported in the perirenal adipose tissues of OLETF diabetic rats during the early stage of diabetes." (PMID 39456161, 2024).
hepatocellular carcinoma (7 papers, 2017 to 2023). A malignant tumor that arises from hepatocytes. "For example, in our study LLM revealed a downregulation of the Aqp7 gene in a set of 20 hepatocellular carcinoma samples (GDS4887 data set)." (PMID 31757200, 2019). "A significative reduction of AQP7 was reported in hepatocellular cancer cells by a recent investigation on 68 patients." (PMID 31757200, 2019). "Similarly, both AQP3 and AQP7 are found in both the nucleus and cytoplasm of hepatocellular carcinoma." (PMID 33917751, 2021). "In hepatocellular carcinoma (HCC), AQP3 was upregulated, and AQP7 and AQP9 were downregulated, being significantly associated with the aggressive features of HCC." (PMID 35187089, 2022). "Auphen was also shown to inhibit AQP7 in adipocytes and was used to unveil a role of AQP3 in keratinocytes autophagy, to suppress growth of hepatocellular carcinoma by downregulating AQP3, and to impair cell migration via AQP3 blockage in colonic epithelia." (PMID 35187089, 2022). "Similar to that observed in the present study, down-regulated expression of aquaporin, AQP7 gene belonging to water channel family, TIMP4 belonging to mettalloproteinases inhibitor family member was also reported in breast and hepatocellular carcinoma at transcript level." (PMID 31292488, 2019).
Hyperglycemia (7 papers, 2019 to 2025). An increased concentration of glucose in the blood. "Mice deficient for AQP7 (Aqp7−/−) cannot release glycerol into circulation in response to adrenergic stimulation and were protected from hyperglycemia during HS." (PMID 33097799, 2020). "Our studies in the Aqp7 mouse model show a dose-dependent increase in body weight, hyperglycemia, hyperinsulinemia, and increased fat accumulation - particularly in the VAT." (PMID 41203811, 2025). "The mice’s genetic background are likely influencing the phenotype of the Aqp7 knockout mice, i.e., the presence of hyperinsulinemia combined with the presence or absence of hyperglycemia, or the presence of normoglycemia with undetermined insulin levels." (PMID 37681902, 2023). "Aqp7 knockout mice displayed hyperinsulinemia with either hyperglycemia or normoglycemia, or normal insulin and glucose levels." (PMID 31614661, 2019). "AQP3 and AQP7 have been described to modulate glycerol efflux from adipose tissue, thus controlling the glycerol influx into hepatocytes, via AQP9 to prevent the excessive lipid accumulation and the subsequent aggravation of hyperglycemia." (PMID 33465153, 2021).
Hepatic steatosis (5 papers, 2014 to 2021). Steatosis is a term used to denote lipid accumulation within hepatocytes. "Thus, NEAT1 participates in the activation of ERα to modulate AQP7-associated hepatic steatosis." (PMID 32759784, 2020). "The 3′ terminal region of nuclear enriched abundant transcript 1 (NEAT1) has been shown to interact with ERα to enhance expression of Aquaporin 7 (AQP7) and subsequently inhibit liver steatosis." (PMID 32759784, 2020). "A recent study showed that treatment with estrogen protects against ovariectomy-induced hepatic steatosis by increasing hepatocyte AQP7 expression." (PMID 30042691, 2018). "Liver AQP7 was therefore suggested to play an important role in lipogenesis representing a potential target for the prevention and treatment of fatty liver disease in postmenopausal women." (PMID 30042691, 2018). "In conclusion, Qutanhuoxue decoction can reduce the degree of hepatic steatosis, which may be closely related to the increase of AQP7 expression in adipose tissue and the decrease of AQP9 expression in liver." (PMID 31275413, 2019). "Furthermore, the membrane protein AQP7, which correlates with hepatic steatosis, was also decreased in OPN-KO mice." (PMID 24871103, 2014). "Leire Méndez-Giménez found that sleeve gastrectomy, a widely applied bariatric surgery procedure, restores the coordinated regulation of fat-specific AQP7 and liver-specific AQP9, thereby improving whole-body adiposity and hepatic steatosis." (PMID 31275413, 2019).
Hyperinsulinemia (5 papers, 2018 to 2025). An increased concentration of insulin in the blood. "However, depending on their genetic background, these Aqp7 deficient mice presented different phenotypes characterized by either normal glycaemia with underdetermined insulinemia, normal glycaemia with hyperinsulinemia, or hyperglycaemia and hyperinsulinemia." (PMID 30042691, 2018). "Moreover, the AQP-7 knockout mice showed hyperinsulinemia, decreased size and mass of beta cells, increased glucose-induced and basal insulin release, and increased triglycerides and glycerol contents." (PMID 40419958, 2025). "Moreover, the AQP7 KO mice had reduced β-cells mass and increased proinsulin biosynthesis with marked fasting hyperinsulinemia." (PMID 29300344, 2018). "In contrast to these results, no hyperinsulinemia was found when investigating the role of AQP7 in pancreatic β-cells in the AQP7 KO mouse line where adipocyte hypertrophy and marked glyceroluria had previously been demonstrated." (PMID 29300344, 2018).
inflammatory bowel disease (5 papers, 2016 to 2024). A spectrum of small and large bowel inflammatory diseases of unknown etiology. "In the human small intestine, reduced levels of AQP7 mRNA were correlated with inflammatory bowel diseases such as Crohn’s disease or ulcerative colitis." (PMID 34679037, 2021). "Moreover, in pathological conditions, AQPs localization may shift from apical to basolateral membranes, as observed for AQP7 in colon inflammatory bowel disease patients." (PMID 33465153, 2021). "The reduced mRNA expression of several AQPs (AQP1, AQP3, AQP7 and AQP8) in human intestinal mucosa has been demonstrated at the early stage of inflammatory bowel diseases (IBD), including Crohn’s disease and ulcerative colitis." (PMID 27589719, 2016).